FEM1C (fem-1 homolog C)
Description:
Substrate-recognition component of a Cul2-RING (CRL2) E3 ubiquitin-protein ligase complex of the DesCEND (destruction via C-end degrons) pathway, which recognizes a C-degron located at the extreme C terminus of target proteins, leading to their ubiquitination and degradation. The C-degron recognized by the DesCEND pathway is usually a motif of less than ten residues and can be present in full-length proteins, truncated proteins or proteolytically cleaved forms. The CRL2(FEM1C) complex specifically recognizes proteins with an arginine at the C-terminus: recognizes and binds proteins ending with -Lys/Arg-Xaa-Arg and -Lys/Arg-Xaa-Xaa-Arg C-degrons, such as SIL1 or OR51B2, leading to their ubiquitination and degradation. The CRL2(FEM1C) complex mediates ubiquitination and degradation of truncated MSRB1/SEPX1 selenoproteins produced by failed UGA/Sec decoding. Promotes ubiquitination and degradation of SLBP.
Synonyms: KIAA1785; EUROIMAGE686608; EUROIMAGE783647; FEM1A
Tractability: Small molecule: a structure with a bound ligand is known. PROTAC: ubiquitination databases record sites on it.
Gene: Protein-coding gene on chromosome 5 (115,520,908 to 115,544,775, reverse strand). Ensembl gene ENSG00000145780.
Subcellular location (Human Protein Atlas): Nucleoplasm
Pathways (Reactome):
Metabolism of proteins: Neddylation
Gene Ontology:
Molecular function: protein binding; ubiquitin-like ligase-substrate adaptor activity
Biological process: proteasome-mediated ubiquitin-dependent protein catabolic process; ubiquitin-dependent protein catabolic process via the C-end degron rule pathway; protein ubiquitination
Cellular component: Cul2-RING ubiquitin ligase complex; nucleoplasm; cytosol; ubiquitin ligase complex; cytoplasm
Genetic constraint (gnomAD): Loss-of-function variants: 15 observed, 39.46 expected, observed/expected ratio (o/e) 0.38, 90% interval 0.25 to 0.58. The upper end of that interval is the gene's LOEUF score, 0.58, which puts it in group 2 of 6, group 1 being the genes least tolerant of losing a copy. Missense variants: 532 observed, 788.85 expected, observed/expected ratio (o/e) 0.67, 90% interval 0.63 to 0.73. Synonymous variants: 287 observed, 288.51 expected, observed/expected ratio (o/e) 0.99, 90% interval 0.9 to 1.1.
Homologues: Orthologues: chimpanzee FEM1C (100% identical), macaque FEM1C (100% identical), pig FEM1C (99% identical), dog FEM1C (99% identical), rabbit FEM1C (99% identical), rat Fem1c (99% identical), mouse Fem1c (99% identical), tropical clawed frog fem1c (90% identical), zebrafish fem1c (54% identical). Paralogues in human: FEM1A (70% identical), FEM1B (41% identical), ANKRD33 (12% identical), ANKRD33B (12% identical).
Diseases named in the same sentence as FEM1C in open-access papers:
FEM1C is named in the same sentence as 7 diseases in open-access papers, as found by Europe PMC text mining. Sharing a sentence is not in itself a finding about the gene and the disease. The quoted sentences say what the papers report.
colorectal cancer (2 papers, 2023 to 2025). A primary or metastatic malignant neoplasm that affects the colon or rectum. "FEM1C, though still poorly understood in this context, belongs to the highly conserved VHL-box proteins family, involved in cell cycle regulation and cell proliferation via the Cullin 2-RING E3 ubiquitin ligase complex, and its downregulation has been linked to colorectal cancer progression." (PMID 41359656, 2025).
developmental delay (1 paper, 2023). "Using exome sequencing to diagnose a pediatric patient with developmental delay, pyramidal signs and limb ataxia, we identified a de novo missense variant c.376G>C; p.(Asp126His) in the FEM1C gene encoding a cullin-RING ligase substrate receptor." (PMID 36336956, 2023).
Limb ataxia (1 paper, 2023). A kind of ataxia that affects movements of the extremities. "We describe a pediatric case of severe DD, lack of speech, pyramidal signs and limb ataxia associated with a novel de novo variant p.(Asp126His) in the FEM1C gene." (PMID 36336956, 2023).
neurodevelopmental disorder (1 paper, 2023). A behavioral and cognitive disorder with onset during the developmental period that involves impaired or aberrant development of intellectual, motor, or social functions. "Importantly, another de novo variant (Asp126Val) in the same residue of FEM1C was associated with a neurodevelopmental disorder." (PMID 36336956, 2023).
FEM1C also shares sentences with these, for which no sentence is quoted: bladder urothelial carcinoma (1 paper); cancer (1); uterine corpus endometrioid carcinoma (1).